TNF (tumor necrosis factor)
Diseases named in the same sentence as TNF in open-access papers (continued):
Sharing a sentence is not in itself a finding about the gene and the disease.
Obesity (continued). "Indeed, TNF and many other inflammatory mediators are commonly found to be upregulated in insulin resistance and obesity." (PMID 36613595, 2022). "With the development of obesity, the adipose tissue undergoes some molecular and cellular adaptations with a significant generation of pro-inflammatory molecules such as tumor necrosis factor α (TNFα) and interleukin 6 (IL-6)." (PMID 35370992, 2022). "Thus, the transcriptional profiles of the TNF-α and IL-1β genes reported in this study agree with the expected inflammatory state characteristics of obesity induced by diet." (PMID 36235679, 2022). "IL-6 and TNF-α were associated with a slightly higher grade of inflammation in children with obesity than the normal-weighted controls; however, this was not statistically significant." (PMID 33883996, 2021). "It is considered that IL-6, together with TNF-α, could play a key role in developing insulin resistance and pathologies related to obesity." (PMID 34568404, 2021). "The IL-23/17 axis inhibitors thus appear more indicated than anti-TNF-α antibodies in obesity." (PMID 34829740, 2021). "Obesity is also associated with increased circulating concentrations of inflammatory markers such as C-reactive protein (CRP), interleukin-6 (IL-6), and tumor necrosis factor (TNF)-α." (PMID 33498671, 2021). "The obesity state can elevate proinflammatory adipokines through adipose tissue inflammation, such as interleukin-6 (IL-6), tumor necrosis factor-alpha (TNF-α) and free fatty acids (FFAs), which can induce both insulin resistance and compensatory hyperinsulinism." (PMID 34603211, 2021). "Obesity, hypertension and type 2 diabetes are the most common comorbidities, that lead to increased levels of inflammatory biomarkers such as interleukin-6 (IL-6) and tumor necrosis factor-α (TNF-α)." (PMID 33945586, 2021). "TNFα is a key molecule linking obesity and insulin resistance." (PMID 34576943, 2021). "Adipokines, including IL-6 and TNF-α, are reported to induce inflammation in obesity." (PMID 34074279, 2021). "While this was unexpected because increasing obesity is commonly associated with OAT inflammation, it may be explained by previous observations that adipose TNF levels are less variable in subjects with BMIs >40, as is the case in our samples." (PMID 34103691, 2021). "Chronic inflammation involves obesity and elevates insulin resistance, which gives rise to an abnormal production adipocytokines such as leptin, tumor necrosis factor α, prothrombotic mediator plasminogen activator inhibitor-1 (Pal-1), interleukin-1, and interleukin-6." (PMID 35223819, 2021). "Inflammatory cytokines such as TNF-α and IL-6, highly abundant in obesity and T2D, bind to receptors on the cardiomyocyte surface which triggers downstream activation of NF-κB and other central regulators of cell metabolism with differential impact on cardiomyocyte function." (PMID 34671656, 2021). "Another possible explanation could be the state of chronic inflammation represented by obesity, in which adipocyte hypertrophy and hypoxia lead to the production of pro-inflammatory cytokines, such as TNF-alpha." (PMID 35010957, 2021). "The possible mechanisms may be due to obesity-related molecules, such as leptin, adiponectin, TNF-α, and IL-6, and their subsequent signal pathways." (PMID 33842335, 2021). "Although, the pathogenesis of obesity and its association to metabolic disorders like T2DM is complicated, adipose tissue polarized macrophages to increase secretion of pro‐inflammatory cytokines such as TNF-α." (PMID 34372916, 2021). "In addition, obesity promotes liver inflammation and tumorigenesis by enhancing the expression of interleukin-6 (IL-6) and tumor necrosis factor (TNF), which further activates several pro-oncogenic pathways." (PMID 35154012, 2021). "IL-6 and TNF-α are classic obesity-related inflammatory factors." (PMID 34836242, 2021). "ACSL1 is upregulated by LPS and TNFα, both of which are elevated in obesity." (PMID 34299302, 2021).
Obesity (continued). "Obesity is currently presented as a pro-inflammatory state with an expansion in the outflow of inflammatory cytokines, such as interleukin-6 (IL-6) and tumor necrosis factor-alpha (TNF-α), alongside the expanded emission of leptin." (PMID 33946540, 2021). "In addition, obesity promotes liver inflammation by enhancing secretion of interleukin (IL) 6 and tumor necrosis factor (TNF)." (PMID 33546219, 2021). "A study that investigated obesity-related NAFLD found that CD8+ T cells regulate obesity and hyperlipidemia-associated NASH through the production of cytokines, such as IL-10 and TNFα, which drive the recruitment of macrophages and activation of hepatic stellate cells (HSCs)." (PMID 34830072, 2021). "In our cohort, we could confirm that boys with severe obesity have higher levels of TNFα than girls." (PMID 33986456, 2021). "The obesity-related asthma phenotype is also associated with the presence of increased interleukins levels, such as TNF-α and IL-1β in the lung, even in the absence of an antigenic challenge." (PMID 33418879, 2021). "Elevated levels of TNF-α are persistently expressed in obesity and metabolic syndrome." (PMID 33859296, 2021). "Obesity, independent from AF, has also been linked to systemic inflammation (elevated levels of C‐reactive protein, IL‐6 and tumor necrosis factor‐α [TNF‐α]), due to IL‐6 and TNF‐α production from (visceral) adipose tissue." (PMID 33769583, 2021). "In addition, another study demonstrated that treatment ofmacrophages with 5-AZAdC increased ARG1 expression in these cells, and increased the population of F4/80+CD206+ M2 macrophages and reduced TNF-α production, controlling inflammation response in obesity." (PMID 33921194, 2021). "A parallel, double-blind, placebo-controlled, randomized study reported the ability of aged garlic supplementation to modulate immune cell distribution and decrease serum tumor necrosis factor (TNF)-α and interleukin (IL)-6 levels in healthy obese adults, thus reducing obesity-induced inflammation." (PMID 34444755, 2021). "Our results suggest that plasma adiponectin levels may play a more important role than TNFα in influencing plasma SHBG levels in our prepubertal population with obesity." (PMID 33689083, 2021). "However, in the course of metabolic diseases related to obesity, both elevated cytokines (e.g., TNFα) and free fatty acid (FFA) trigger serine phosphorylation of IRS-1 by stress kinases, resulting in the development of insulin resistance." (PMID 34070553, 2021). "Since the increased TNF-α expression and oxidative stress are two primal level pathophysiological triggers in obesity, it was intriguing to further explore whether these two agents could modulate IL-8 and MCP-1 expression in monocytic cells." (PMID 34638857, 2021). "The present study demonstrated that 12 weeks of synbiotic supplementation significantly reduced the physical parameters as well as the inflammation markers IL-6, IL-1β, TNF-α and other obesity markers including LPS, zonulin, 5-HIAA, and QA in Thai obese subjects." (PMID 34359450, 2021). "Prior studies also demonstrated that TNF-α combined with other types of pro-inflammatory cytokines contributed to the development of type II diabetes, obesity and obesity-induced insulin resistance, which suggested TNF-α played as an essential role in the development of MS12–15." (PMID 33589701, 2021). "It has been suggested that chronic inflammation in obesity is apparent, with an increased level of interleukin-6, adipokines and pro-inflammatory cytokines (e.g., TNF-alpha, interferon), inducing a chronic low-grade inflammatory state and impairing immune response." (PMID 33556150, 2021). "Previously, obesity was shown to promote a type 1 inflammatory response, including infiltration of activated T cells, expansion of M1 macrophages, and secretion of inflammatory cytokines, including tumor necrosis factor-α (TNF-α), IL-6, and IL-1β." (PMID 34073755, 2021).
Obesity (continued). "Most adipokines, including leptin, tumor necrosis factor-alpha (TNF-α), interleukin 6 (IL-6), resistin, or retinol-binding protein 4 (RBP4), are augmented in the obese state and promote inflammatory reactions, leading to obesity-associated comorbidities." (PMID 34948320, 2021). "In addition, knowing that obesity itself results in an inflammatory state in metabolic tissues, the release of inflammatory cytokines IL-6, IL-8 and TNF-α from infected lung tissues can exacerbate the pro-inflammatory picture in patients." (PMID 34684105, 2021). "Indeed, circulating levels of several inflammatory cytokines (i.e., CRP, IL‐1β, IL‐6, IL‐8, MCP‐1, and TNFα) have been shown to be increased in obesity." (PMID 34110720, 2021). "Additionally, it has been reported that individuals with high levels of C-peptide, interleukin-6 (IL-6), tumor necrosis factor-α (TNF-α), as well as low level of adiponectin had significantly higher risk of ccRCC, all these biomarkers are obesity-related." (PMID 34621242, 2021). "Thus, in IBS with diarrhea, especially in its comorbid course with obesity, there is an imbalance of cytokines, which was manifested through a reduced content of IL-10 with increasing levels of TNFα and TGFβ1." (PMID 34621378, 2021). "Since TNF-α is invariably elevated in obesity and metabolic syndrome, expression of inflammatory phenotypic markers in monocytes/macrophages could have been induced by TNF-α." (PMID 33859296, 2021). "TNF-α has been proposed as one of the primary humoral links between obesity and insulin resistance." (PMID 34680177, 2021). "The immune dysregulations include increased levels of inflammatory markers such as C - reactive protein (CRP), interlukin-6 (IL-6), tumour necrosis factor alpha (TNF alpha), and other cytokines indicating insulin and leptin resistance, obesity, inflammation, and higher rates of metabolic syndrome." (PMID 34895175, 2021). "Furthermore, increased levels of IL-6 and TNF- α have been reported both in depressed patients and in those with obesity." (PMID 33809270, 2021). "Chemerin levels correlate with serum concentrations of TNF-α, IL-6, and CRP, and they may reflect the inflammatory status associated with obesity." (PMID 33921758, 2021). "Certain cytokines, such as tumor necrosis factor (TNF), interleukin (IL) 1 or interferon, seem to contribute to the relationship between obesity-associated inflammation and insulin resistance since disruption of these signals resulting in improved glucose homeostasis in mouse models." (PMID 34207683, 2021). "Being skewed toward a proinflammatory state, alterations in adipocyte-intrinsic cellular metabolism impacts adipocyte-immune cell crosstalk via changes in adiponectin, leptin, and IL-6, as well as other pro-inflammatory mediators (e.g., TNF, IL-1, type I IFNs, etc.)is dysregulated during obesity." (PMID 33958704, 2021). "Furthermore, to evaluate the potential of SIT to attenuate obesity induced inflammation and thus insulin resistance, we quantified the gene and protein expression of proinflammatory cytokines including TNF-α and IL-6 in the adipose tissues of rats under study." (PMID 33917607, 2021). "Adipose tissue is also an active endocrine organ that can secrete some hormones or cytokines (e.g., resistin, tumor necrosis factor-α and complement D) to participate in the immune response and treatment of obesity or cardiovascular diseases and other physiological and pathological processes." (PMID 34571718, 2021). "Patients with obesity have higher concentrations of circulating tumor necrosis factor-alpha (TNF-a), interleukin-6, and C-reactive protein (CRP); this low grade chronic inflammatory state may be involved in initiating cytokine storms in patients with COVID-19." (PMID 34068824, 2021). "Obesity may also trigger inflammatory pathways that increase TNF-α production in the adipose tissue, which in turn induce aromatase expression in adipose fibroblasts." (PMID 34426770, 2021).
Obesity (continued). "It has been reported that diet‐induced obesity activates adipose tissue macrophages (ATM) into pro‐inflammatory M1 macrophages that produce a variety of pro-inflammatory cytokines such as TNF‐α and IL‐6, which contribute to the development of diabetes and atherosclerosis." (PMID 33737713, 2021). "Alternatively, obesity induced by high-fat diet instead of age may have resulted in more severe obesity and obesity-induced inflammation, with for example increased levels of TNF, and thus subsequently a better bone-protective effect upon adipose tissue loss." (PMID 34238965, 2021). "Luminex analysis showed that in the HFD-induced obesity mouse model, there was an obvious increase in serum proinflammation cytokines such as TNF-α, MCP-1, IL-12, IL-1β, IL-6, CCL3, CXCL16, and Resistin, which were further alleviated significantly in the CD226KO group." (PMID 34823548, 2021). "Although both our acute inflammatory LPS model and chronic inflammatory obesity model resulted in similar adverse embryo outcomes and placental apoptosis, there seem to be differences in how iron excess alters TNFα signaling in acute and chronic inflammatory settings." (PMID 34188052, 2021). "Obesity-associated chronic low-grade inflammation characterized by high levels of plasmatic inflammatory markers [C-reactive protein, interleukin 6 (IL6) or tumor necrosis factor α (TNFα)] largely contributes to the development of the obesity-related chronic metabolic diseases." (PMID 35024040, 2021). "This study demonstrated that MLB supplementation attenuated obesity-associated skeletal muscle atrophy in HFD mice through the regulation of the PI3K/Akt/FoxO1 and TNF-α/NF-κB signaling pathways, leading to the inhibition of muscle-specific ubiquitin E3 ligase expression." (PMID 35010979, 2021). "Indeed, increased levels of TNF-α, IL-6, MMP-9, and VEGF have been extensively documented in obesity and found to be associated with metabolic inflammation, hyperglycemia, insulin resistance and progression to type-2 diabetes or metabolic syndrome." (PMID 34230580, 2021). "Interestingly, the IL-6 and TNFα levels are significantly higher in adipose tissue than in liver, in patients with severe obesity, suggesting that adipose tissue is the main cytokine source in the progression of steatohepatitis." (PMID 34073834, 2021). "In addition, obesity promotes inflammation by increasing pro-inflammatory cytokines, such as tumor necrosis factor-alpha and interleukin-6, and increases cardiovascular disease risk." (PMID 33855037, 2021). "Offspring of the HFD group demonstrated higher mRNA levels of chemokine receptor-2 and tumor necrosis factor-α (TNF-α) and reduced levels of glucose transporter-4 (GLUT4), which indicates higher risk of developing obesity and metabolic disorders during adolescence." (PMID 34368253, 2021). "TNFα increases the production of MCP-1 during conditions of obesity." (PMID 34299302, 2021). "Thus, the obesity-related decrease in adiponectin further contributes to a dysregulated TNF-α signaling." (PMID 34211985, 2021). "Previous data suggested that obesity and high-fat meal could result in the increase of tumor necrosis factor α (TNF-α) and endothelial dysfunction, which may lead to the deterioration of metabolic indicators." (PMID 34368367, 2021). "Furthermore, TNFα expression is increased in obesity, further inhibiting the vasodilator effects of insulin in skeletal muscle, reducing blood flow and glucose uptake, and leading to type-II diabetes." (PMID 33687595, 2021). "These include obesity-related paradoxically increased mobilization of endothelial progenitor cells, increased ghrelin sensitivity, decreased thromboxane production, and decreased TNF levels." (PMID 34819090, 2021). "The increased levels of IL-6 and TNF-α in obesity could also affect endothelial NO synthase expression." (PMID 34436493, 2021).
Obesity (continued). "In obesity, excessive fat accumulation in adipose tissues promotes chronic low-grade inflammation related to produce a variety of pro-inflammatory cytokines, such as interleukin-6 (IL-6), interleukin-1β (IL-1β) and tumor necrosis factor-α (TNF-α)." (PMID 34681074, 2021). "This is not surprising, as cytokines of innate immunity such as interleukin 6 (IL-6) and tumor necrosis factor alpha (TNF-α) may be produced by adipocytes as a result of low-grade inflammation of white adipose tissue which characterizes obesity." (PMID 33809270, 2021). "Adipose tissue hyperplasia during obesity induces the secretion of adipocytokines such as leptin, interleukin-6 (IL-6), interleukin-1β (IL-1β), IL-10, TNF-α, monocyte chemo-attractant protein-1, and plasminogen activator inhibitor-1, which are responsible for obesity-related inflammation." (PMID 33946303, 2021). "TNF as an inhibitor of insulin signaling is a major contributor towards obesity-related diseases." (PMID 34372916, 2021). "In addition, empagliflozin decreases the accumulation of M1 macrophages, simultaneously induces the anti-inflammatory M2 macrophage phenotype in liver and white AT, and reduces obesity-related chronic inflammation (such as blood TNFα level)." (PMID 34163481, 2021). "The oral administration of probiotics like Bifidobacterium longum NK49 and Lactobacillus plantarum NK3 could improve obesity and osteoporosis in mice by completing intestinal barrier integrity and further modulating immune cells with reducing TNF-α expression." (PMID 34579087, 2021). "Furthermore, empagliflozin reduced M1-polarized macrophage accumulation while inducing the anti-inflammatory M2 phenotype of macrophages within white adipose tissue and liver, lowering plasma TNFα levels and attenuating obesity-related chronic inflammation." (PMID 34281221, 2021). "Concentrations of TNF and IL-6 are elevated in depressed individuals compared to healthy ones, while CRP concentrations have been associated with depression scale scores and explained 20% of the obesity-related alteration in depression scores at follow-up." (PMID 33546219, 2021). "These cells are recruited and activated in obesity and have increased expression of TNF-α and IL-1." (PMID 34489979, 2021). "Furthermore, an increase in obesity-induced lipid storage leads to adipose tissue dysfunction and promotes adipocyte secretion of pro-inflammatory cytokines, including TNF-α and IL-6." (PMID 34194325, 2021). "Having seen that HFD or TNFα treatment increases the nuclear accumulation of CRTC2/3 in adipocytes, we searched for downstream CREB target genes that contribute to the inflammatory and metabolic changes associated with obesity." (PMID 34686752, 2021). "Additionally, adipose tissue can also synthesize cytokines such as TNF-∝ and IL-6 thus obesity itself promotes inflammation and potentiates atherogenesis." (PMID 33841183, 2021). "In this first cross-sectional study, examining breast tissue-specific biomarker expression with combined obesity parameters, we found that mean expression levels of IL-6, TNF-α, and LEP were higher in the breast adipose tissue of women with WC ≥ 86 cm, regardless of BMI." (PMID 34426770, 2021). "TNFα and IL-1β are the main obesity-induced proinflammatory cytokine and chemokine, respectively." (PMID 34531738, 2021). "Obesity and metabolic syndrome are accompanied by persistently increased IL-6 and TNF-α levels which may contribute to insulin resistance and deleterious vascular effects." (PMID 34202323, 2021). "Increasing obesity induces the release of chemotactic molecules (e.g., monocyte chemoattractant protein-1) with macrophage infiltration and the release of proinflammatory cytokines, such as TNF-α and IL-6." (PMID 34065158, 2021). "Resistin and TNF-α are directly related to the progression of obesity and diabetes." (PMID 33552386, 2021).